EGFR (epidermal growth factor receptor)
Diseases named in the same sentence as EGFR in open-access papers (continued):
Sharing a sentence is not in itself a finding about the gene and the disease.
non-small cell lung carcinoma (continued). "Patients with EGFR mutations who have advanced-stage non-small cell lung cancer (NSCLC) already receive tyrosine kinase inhibitors (TKIs) as the standard first-line therapy." (PMID 37881485, 2023). "EGFR tyrosine kinase inhibitors (TKIs) are the first-line treatment for advanced EGFR-mutated non-small-cell lung cancer (NSCLC)." (PMID 37886957, 2023). "Mutations in the epidermal growth factor receptor (EGFR) gene are highly prevalent in non-small cell lung cancer, while rare in other cancers." (PMID 36701708, 2023). "In non-small cell lung cancer patients bearing an EGFR mutation, 45% of EGFR mutants bear an L858R mutation." (PMID 36739948, 2023). "This Delphi panel study assessed the level of consensus between medical oncologists on the clinical management of patients with early-stage EGFR-mutated non-small cell lung cancer (NSCLC)." (PMID 36168085, 2023). "Non-Small Cell Lung Cancer displays several genetic mutations including epidermal growth factor receptor." (PMID 38008767, 2023). "Genetic mutations within the EGFR gene are detected in around 12–47% of non-small cell lung cancer (NSCLC) tumors characterized by adenocarcinoma histology." (PMID 37513921, 2023). "The ADAURA clinical study, probing the efficacy of adjuvant osimertinib therapy, has unveiled notable amelioration in disease-free survival for early and locally advanced non-small cell lung carcinoma patients bearing EGFR mutations." (PMID 37686123, 2023). "They account for approximately 10% of the mutated EGFR population and are found in approximately 2% of all non-small-cell lung cancers (NSCLCs)." (PMID 37622996, 2023). "We know that the EGFR mutation Thr790Met is considered pathogenic because it confers resistance to tyrosine kinase inhibitors (Gefitinib TKIs), which are commonly used to treat non-small-cell lung cancer (NSCLC) patients with activating EGFR mutations." (PMID 37508780, 2023). "The US Food and Drugs Administration (FDA) has recently approved dacomitinib as a first-line treatment for patients suffering from non-small cell lung cancer (NSCLC) with epidermal growth factor receptor (EGFR) mutations." (PMID 36903599, 2023). "Gallic acid reduces the amount of EGFR via speeding up EGFR transformation, causing death in EGFR mutant non-small cell lung cancer cells (MSCLC), although proteasome antagonists can counteract this action." (PMID 37110167, 2023). "The most common driver gene mutation of non-small cell lung cancer (NSCLC) in East Asians is epidermal growth factor receptor (EGFR) mutation." (PMID 37869096, 2023). "Central nervous system (CNS) metastases including brain metastases (BM) and leptomeningeal metastases (LM) are frequent in epidermal growth factor receptor (EGFR)-mutated non-small cell lung cancer (NSCLC), and are correlated with poor outcomes." (PMID 36870951, 2023). "For example, tyrosine kinase inhibitors (TKIs) show significant clinical benefit in patients with non-small cell lung cancer (NSCLC) harboring epidermal growth factor receptor (EGFR)-sensitizing mutations." (PMID 37372399, 2023). "EGFR mutations (e.g., exon 19 deletions, L858R point mutation) increase sensitivity to EGFR inhibitors in non-small-cell lung cancer (NSCLC)." (PMID 38202898, 2023). "In this review, we highlight the proteome and phosphoproteomic analyses of non-small cell lung cancer (NSCLC) as well as the proteome analysis of biofluid specimens that associate with acquired resistance in response to different generations of EGFR-TKI." (PMID 36902280, 2023). "Lung adenocarcinoma is the most common histological type of non-small cell lung cancer and is more prone to EGFR mutations than other subtypes." (PMID 36983578, 2023). "Small cell lung cancer (SCLC) transformation serves as a significant mechanism of resistance to tyrosine kinase inhibitors (TKIs) in advanced non-small cell lung cancer (NSCLC) with epidermal growth factor receptor (EGFR) mutations." (PMID 38188289, 2023).
non-small cell lung carcinoma (continued). "In Asians, 53% of non-small cell lung cancer (NSCLC) progression is induced by epidermal growth factor receptor (EGFR) mutations, such as the L858R mutation, exon 19 deletion, and exon 20 insertion." (PMID 37841421, 2023). "Among the recommended targeted cancer drug indications, only gefitinib for EGFR mutation-positive advanced non-small cell lung cancer (NSCLC) met the WHO EML OS benefit criterion." (PMID 37775106, 2023). "Non-small cell lung cancer (NSCLC) harboring activating mutations in the epidermal growth factor receptor (EGFR) tyrosine kinase domain are typically treated with the EGFR tyrosine kinase inhibitor, erlotinib." (PMID 37097392, 2023). "Typically, EGFR mutations are associated with high response rates to anti-EGFR TKIs in metastatic non-small-cell lung cancer." (PMID 36980614, 2023). "The detection of epidermal growth factor receptor (EGFR) mutations in patients with non-small cell lung cancer is critical for tyrosine kinase inhibitor therapy." (PMID 37407963, 2023). "Mutations in the epidermal growth factor receptor (EGFR) have been implicated in nearly one-third of non-small-cell lung cancers." (PMID 37234142, 2023). "Over the past decade, the development of EGFR tyrosine kinase inhibitors (TKIs) has revolutionized the therapy of non-small cell lung cancer (NSCLC) with mutated epidermal growth factor receptor (EGFR) gene." (PMID 36817153, 2023). "EGFR mutations, usually ligand-independent activating mutations, are well-known oncogenic events in non-small-cell lung cancers." (PMID 36980614, 2023). "Overexpression or mutation in the EGFR gene leads to various types of cancer, i.e., non-small cell lung cancer, breast, and pancreatic cancer." (PMID 37264083, 2023). "In contrast, EGFR mutations in non-small cell lung cancer cells render them more susceptible to SLC7A11 inhibition or cysteine deprivation because intracellular cysteine promoted survival EGFR-mutant cells independent of GSH-relater redox balance." (PMID 36864513, 2023). "The mechanism of drug resistance of first/second-generation EGFR-TKIs in non-small cell lung cancer (NSCLC) is a secondary gene mutation, such as TK domain mutation (T790M), MET amplification, and RAS mutation." (PMID 37730961, 2023). "Combining ICIs with EGFR inhibitors in non-small-cell lung cancer (NSCLC) with EGFR mutations only triggered toxicities and did not improve efficacy." (PMID 37345194, 2023). "EGFR mutation or overexpression has an essential role in tumorigenesis in different types of cancers, including non-small-cell lung cancer (NSCLC), breast cancer, colorectal cancer, and gastric carcinoma." (PMID 36831545, 2023). "For example, a study conducted in 2016 by Leduc and al. exploring the incidence rates of EGFR mutations in patients with non-small cell lung cancer of Caribbean origin found a higher rate of a mutation predictive of response to a particular targeted therapy." (PMID 36928660, 2023). "Osimertinib has emerged as an important tool in the treatment of non-small cell lung cancers (NSCLC) with certain activating mutations of epidermal growth factor receptor (EGFR)." (PMID 37898814, 2023). "A non-small-cell-lung-cancer patient with cerebral metastasis presenting an atypical exon 20 mutation in the EGFR gene had a long-lasting tumor cotrol on mulimodal treatment with osimertinib and stereotaxic radiotherapy on oligoprogressing lesions." (PMID 37465107, 2023). "Epidermal growth factor receptor (EGFR)-activating mutations have been targeted for the treatment of non-small cell lung cancer (NSCLC)." (PMID 37569564, 2023). "Gefitinib is a potent and selective orally active growth factor receptor (EGFR)-tyrosine kinase inhibitor that is commonly used to treat advanced non-small cell lung cancer patients with activating EGFR mutations." (PMID 37960757, 2023).
non-small cell lung carcinoma (continued). "Hundreds of synthetic long peptides, RNA-, DNA-, and dendritic cell-based vaccines have reached clinical validation trials, and one successful example is a neoantigen peptide vaccine for EGFR-mutated non-small cell lung cancer." (PMID 37047684, 2023). "Non-small cell lung cancer (NSCLC) is often driven by mutations in the epidermal growth factor receptor (EGFR) gene." (PMID 38035047, 2023). "It is being investigated for the treatment of non-small cell lung cancer (NSCLC) with EGFR mutations." (PMID 37795080, 2023). "With the advancement of targeted therapies, epidermal growth factor receptor tyrosine kinase inhibitors have become the preferred initial treatment for patients with advanced epidermal growth factor receptor (EGFR)-mutated non-small cell lung cancer." (PMID 37653755, 2023). "Another study has reported a concordance rate of 70% to 80% between liquid biopsies and tissue biopsies in detecting EGFR mutations in non-small-cell lung cancer patients." (PMID 37240238, 2023). "The interaction of αvβ3 integrin with osteopontin activates the FAK signaling pathway to suppress apoptosis, resulting in epidermal growth factor-tyrosine kinase inhibitor (EGFR-TKI) resistance in non-small cell lung cancer with EGFR-mutation." (PMID 38136623, 2023). "We studied the circulating tumor DNA (ctDNA) of 38 EGFR-mutated non-small cell lung cancer patients at diagnosis in different moments of their disease by liquid biopsy techniques." (PMID 37510091, 2023). "For example, the use of liquid biopsy has now been implemented for several years for therapeutic purposes and the detection of resistance mechanisms in non-small cell lung cancer patients with EGFR mutations treated with anti-EGFR therapies." (PMID 37958343, 2023). "Gefitinib (GE) is a first-line epidermal growth factor receptor (EGFR) tyrosine kinase inhibitor (TKI) for patients with advanced non-small cell lung cancer (NSCLC) carrying EGFR activating mutations." (PMID 35530301, 2022). "Recently, we demonstrated that integrin αV is a key part of the drug resistance mechanism of EGFR-mutated non-small-cell lung cancer." (PMID 35597804, 2022). "We focus on EGFR-mutated non-small-cell lung cancer treated with EGFR-TKI, but we also describe similarities in other oncogenic contexts upon targeted therapies or chemotherapies." (PMID 35681591, 2022). "Approximately 20% of patients with non-small cell lung cancer have mutations in the EGFR gene, for which targeted tyrosine kinase inhibitor therapy provides significant treatment benefit." (PMID 35202431, 2022). "Osimertinib is a third-generation epidermal growth factor receptor-tyrosine kinase inhibitors (EGFR-TKIs) capable of overcoming non-small cell lung cancer (NSCLC) with EGFR T790M mutation." (PMID 36617470, 2022). "The upfront treatment of advanced epidermal growth factor receptor (EGFR)-mutated non-small cell lung cancer (NSCLC) is rapidly changing." (PMID 34773474, 2022). "Up to now, the European Medicines Agency (EMA) and the FDA have approved epidermal growth factor receptor (EGFR) mutation testing using ctDNA in non-small-cell lung cancer (NSCLC) patients." (PMID 36422072, 2022). "In non-small-cell lung carcinoma, combination atezolizumab treatment has been shown to improve overall survival rates in patients with EGFR mutations." (PMID 36498915, 2022). "Osimertinib is a third generation oral TKI known for its utility in targeting EGFR with T790M mutations in non-small cell lung cancer (NSCLC)." (PMID 35603818, 2022). "Resistance to gefitinib remains a major obstacle for the successful treatment of non-small cell lung cancer (NSCLC) with epidermal growth factor receptor (EGFR) mutations." (PMID 34996416, 2022). "The correlation between epithelial-to-mesenchymal transition and resistance to erlotinib (an EGFR tyrosine kinase inhibitor effective in the presence of EGFR activating mutations) has been demonstrated in non-small cell lung cancer." (PMID 36556139, 2022).
non-small cell lung carcinoma (continued). "Case summary: Here, we report the case of a 57-year-old man with advanced non-small cell lung cancer (NSCLC) with a rare EGFR exon 20 N771_P772insH mutation." (PMID 36059942, 2022). "Since the first discovery of EGFR-tyrosine kinase inhibitors (TKIs), they have become the gold standard treatment for EGFR-mutated non-small cell lung cancer." (PMID 35740609, 2022). "Top-ranked virtual hit compounds binding to the allosteric site of the EGFR enzyme can function as strong EGFR inhibitors in the treatment of non-small cell lung cancer mutations." (PMID 35883434, 2022). "ARCHER-1050 showed that this agent can improve progression-free survival and overall survival in advanced non-small cell lung cancer patients with sensitive EGFR mutation compared to gefitinib." (PMID 35305596, 2022). "The most successful application example of 18F-FDG PET/CT imaging is prediction the survival outcomes and guidance the targeted therapy in thousands of non-small cell lung cancer with EGFR mutations involving hundreds of research articles 51-53." (PMID 36168616, 2022). "Epidermal growth factor receptor (EGFR) mutation is one of the main oncogenic drivers of non-small-cell lung cancer (NSCLC)." (PMID 36091840, 2022). "Tyrosine kinase inhibitors (TKIs) are a significant treatment strategy for the management of non-small cell lung cancer (NSCLC) with epidermal growth factor receptor (EGFR) mutation status." (PMID 36276079, 2022). "Epidermal growth factor receptor (EGFR)-tyrosine kinase inhibitors (TKIs) are effective targeted therapy drugs for advanced non-small cell lung cancer (NSCLC) patients carrying sensitized EGFR mutations." (PMID 35095099, 2022). "In this study, we innovatively developed a fusion prediction model to diagnose EGFR mutations in patients with non-small cell lung cancer by fusing the most widely accepted clinicopathological, radiology, and radiomic features with deep learning features." (PMID 35186727, 2022). "For instance, certain mutations in ErbB1 (EGFR) and the amplification/overexpression of ErbB2 provide important targets for interrogation in non-small cell lung cancer (NSCLC) and breast cancer, respectively." (PMID 36230550, 2022). "Activating mutations in EGFR predict benefit from tyrosine kinase inhibitor therapy for patients with advanced non-small cell lung cancer." (PMID 35202431, 2022). "Some representative drugs, like osimertinib, the first and only targeted drug, are approved for the treatment of non-small cell lung cancer (NSCLC) with epidermal growth factor receptor (EGFR) T790M mutation." (PMID 36104717, 2022). "With remarkable advances in gene sequencing, oncologists have focused attention on precision medicine, and specific gene mutations are now considered biomarkers or therapeutic targets (e.g., EGFR mutations in non-small-cell lung cancer and Gefitinib)." (PMID 36299300, 2022). "Non-small cell lung cancer samples with BRAF variants were less likely than expected to carry also alterations in EGFR and KRAS." (PMID 36275468, 2022). "The prognosis of patients with advanced non-small-cell lung cancer (NSCLC) harboring epidermal growth factor receptor (EGFR) sensitizing mutations has significantly improved with EGFR-tyrosine kinase inhibitor (TKI) therapy." (PMID 34953403, 2022). "We also observed specific enrichment of two other known resistance mutations EGFR T790M and C797S in non-small cell lung cancer, again this is almost certainly induced by treatment with EGFR inhibitors." (PMID 36497297, 2022). "Patients have a good clinical status at this moment, and targeted therapies have better ORR and PFS than QT, as in other pathologies (EGFR mutations in non-small cell lung cancer)." (PMID 35954382, 2022). "Recent publications about the predictive value of 18F-FDG PET/CT-derived radiomics with epidermal growth factor receptor mutation status in non-small cell lung cancer." (PMID 36276079, 2022).
non-small cell lung carcinoma (continued). "This study was to explore the most appropriate radiomics modeling method to predict the progression-free survival of EGFR-TKI treatment in advanced non-small cell lung cancer with EGFR mutations." (PMID 35422007, 2022). "In human non-small cell lung cancer A549 cells, curcumin (10 μΜ) has been shown to promote cell death following x-ray irradiation through inhibition of the epidermal growth factor receptor (EGFR)-associated pathway." (PMID 35203521, 2022). "The co-occurrence of two or more rare variants, known as compound variants, is rare in non-small cell lung carcinoma with epidermal growth factor receptor (EGFR) variants, and the compound variant L833V/H835L in exon 21 of EGFR is extremely rare." (PMID 36531621, 2022). "In non-small cell lung cancer, a common marker of resistance to EGFR tyrosine kinase inhibitors is the EGFR T790M mutation." (PMID 35190695, 2022). "Erlotinib, a tyrosine kinase inhibitor, has been shown to improve the survival of patients with epidermal growth factor receptor (EGFR)-mutated non-small cell lung cancer." (PMID 35575465, 2022). "EGFR tyrosine kinase inhibitors (EGFR-TKIs) have been widely used as first-line drugs in patients with non-small cell lung cancer with EGFR mutation." (PMID 35706930, 2022). "H1975 is the non-small cell lung carcinoma cells, A549 is the adenocarcinomic alveolar basal epithelial cells, and PC 9 is the non-small cell lung cancer with EGFR mutation." (PMID 35625834, 2022). "The most common cancer is non-small-cell lung cancer caused by mutation of EGFR in exon 19 and L858R positions." (PMID 36457709, 2022). "Dual inhibition of the epidermal growth factor receptor (EGFR) and vascular endothelial growth factor pathways for the treatment for EGFR-mutated, metastatic non-small cell lung cancer is supported by previous randomized controlled trials." (PMID 35343086, 2022). "The histological transformation from adenocarcinoma (ADC) to squamous cell carcinoma (SCC) is rare but recurrently occurs post TKI treatment in EGFR-mutated non-small cell lung cancer patients with a very limited number of clinical cases published." (PMID 35692748, 2022). "EGFR gene; Gene mutations; Melting curve; Multiple DNA target Detection; Non-small cell lung cancer." (PMID 36468116, 2022). "Treatment with first- or second-generation epidermal growth factor (EGFR)-tyrosine kinase inhibitors (TKIs) is effective for patients with non-small cell lung cancer (NSCLC) who harbor a sensitizing EGFR mutation." (PMID 35323965, 2022). "An example is the treatment of non-small cell lung cancer (NSCLC) patients expressing EGFR mutations with EGFR tyrosine kinase inhibitors (TKIs)." (PMID 35743639, 2022). "EGFR tyrosine kinase inhibitors (EGFR-TKIs) have been introduced into the first-line treatment of non-small cell lung cancer (NSCLC) after the discovery of kinase-activating mutations of the EGFR gene." (PMID 36568260, 2022). "EGFR is an oncogene that is widely amplified and mutated in several cancer types, including non-small cell lung cancer, glioblastoma, and basal-like breast cancers." (PMID 35654793, 2022). "Brain metastasis in patients with non-small-cell lung cancer (NSCLC) harboring epidermal growth factor receptor (EGFR) mutations is a factor of poor prognosis." (PMID 36612183, 2022). "Studies have shown that approximately 33% of non-small-cell lung cancer (NSCLC) patients with EGFR mutation develop brain metastases (BMs), which was the main cause of mortality in patients with advanced NSCLC." (PMID 36015232, 2022). "Our study aimed to identify epidermal growth factor receptor (EGFR) mutations for TKI treatment in non-small-cell lung cancer (NSCLC) Tunisian patients." (PMID 36011410, 2022). "Case studies have found that epidermal growth factor receptor (EGFR) gene mutation accounts for approximately 70% of the pathogenesis of non-small cell lung cancer in China, representing the most common mutation type." (PMID 35372072, 2022).